UGCG (UDP-glucose ceramide glucosyltransferase)
Diseases named in the same sentence as UGCG in open-access papers (continued):
Sharing a sentence is not in itself a finding about the gene and the disease.
cancer (50 papers, 2004 to 2026). A tumor composed of atypical neoplastic, often pleomorphic cells that invade other tissues. "Collectively, the evidence supports a causal role for UGCG-driven GlcCer accumulation in oncogenesis and positions GlcCer metabolism as a promising, druggable node within metabolic signaling network of cancer." (PMID 41155172, 2025). "Targeting glycosphingolipid (GSL) synthesis by blocking the rate-limiting enzyme glucosylceramide synthase (GCS) encoded by the gene UDP-glucose-ceramide-glucosyltransferase (UGCG) has been considered as an option in cancer therapy." (PMID 39796160, 2024). "UGCG and B4GALT5, which encodes LCS, were significantly elevated in KRAS mutant cancers (n = ~730), and combined high expression of UGCG and B4GALT5 correlated with shortened 5-year survival." (PMID 36709325, 2023). "UGCG overexpression is linked to multidrug resistance development in cancer cells, which is ascribed to the unique ability of UGCG to transfer UDP-glucose to ceramide, which results in de novo synthesis of glucosylceramide (GlcCer, cerebroside)." (PMID 34626204, 2021). "UGCG is linked to pro-cancerous processes such as multidrug resistance development and increased proliferation in several cancer types." (PMID 32424263, 2020). "Increased UGCG synthesis is associated with pro-cancerous processes such as increased proliferation and multidrug resistance in several cancer types." (PMID 31666638, 2019). "Interestingly, six genes among these (ABCB1, FGF2, CXCR4, IL6, PSMB9, and CLU), as well as UGCG, are known to be highly associated with cancer resistance to platinum-based chemotherapy." (PMID 40507922, 2025). "UGCG serves as the pivotal catalytic component in glycosphingolipid biosynthesis and regulation, generating glucosylceramide (GlcCer) de novo, and its increased synthesis is linked to enhanced proliferation in various cancers, promoting pro-cancerous processes." (PMID 40332226, 2025). "This “ceramide–GlcCer switch” represents a critical metabolic adaptation exploited by cancer cells and suggests UGCG and GlcCer metabolism as potential therapeutic targets." (PMID 41155172, 2025). "UGCG has emerged as a compelling therapeutic target in oncology, with robust support from preclinical models across multiple cancer types." (PMID 41155172, 2025). "This metabolic shift is especially relevant in rapidly proliferating cancer cells, which display increased UGCG expression and elevated GlcCer levels, often correlated with multidrug resistance and poor prognosis." (PMID 41155172, 2025). "While RICTOR and ZFX showed similar expression in both normal and cancerous epithelial cells, UGCG expression was elevated in cancer cells compared to normal epithelial cells." (PMID 40934285, 2025). "At the transcriptional level, UGCG expression is tightly linked to PI3K/Akt and MAPK signaling, two core oncogenic pathways frequently activated in cancer." (PMID 41155172, 2025). "In this context, UGCG stands out as both a biomarker of malignancy and a promising therapeutic target, particularly in cancers where ceramide/GlcCer metabolism has been rewired to tip the balance from apoptosis toward survival and proliferation." (PMID 41155172, 2025). "In both the healthy and cancer glycocalyx, MGAT1, COSMC, and UGCG are critical chain initiating enzymes that synthesize N-linked glycans (complex and hybrid), O-linked glycans, and GSLs, respectively, and may play a crucial role in cell signaling, immune evasion, and cancer metastasis." (PMID 39628991, 2024). "The activity of UGCG (UDP-glucose ceramide glucosyltransferase) is related to multidrug resistance and cell proliferation in different cancer types." (PMID 35631574, 2022). "UGCG converts ceramide to glucosylceramide (GluCer), which displayed elevated levels in multidrug-resistant cancer cells." (PMID 34637456, 2021). "It is likely that UGCG/GlcCer have different roles in normal cells compared to cancer cells and are regulated differently." (PMID 34626204, 2021).
cancer (continued). "The role of UGCG as a central metabolic hub is particularly significant in cancer." (PMID 41155172, 2025). "Accordingly, the rationale for our study was to determine whether UGCG overexpression is sufficient to drive cancer phenotypes in liver cells." (PMID 34626204, 2021). "Importantly, the overall survival time of patients with high UGCG expression in tumors decreased significantly as compared to patients with low UGCG expression suggesting a potential impact of UGCG expression on cancer prognosis and patient survival." (PMID 34638879, 2021). "Moreover, enhanced ceramide glycosylation by UGCG has been shown to confer multidrug resistance of cancer cells and to selectively maintain pluripotency properties of cancer stem cells." (PMID 32582529, 2020). "The in our study revealed mechanisms give new insights into the important role of UGCG in cell energy metabolism and may contribute to better understanding of cancer cell adaption to poor nutritional supply." (PMID 31666638, 2019). "The revealed cellular mechanisms give new insights into the role of the UGCG in cancer cell energy metabolism and may contribute to better understanding of cancer cell adaption to poor nutritional supply." (PMID 31666638, 2019). "Interestingly, the UGCG is also overexpressed in several cancer types and correlates with multidrug resistance protein 1 (MDR1) gene expression." (PMID 29409484, 2018). "In general, the balance between Cer and HexCers as well as the rate-limiting enzymes in Cer glycosylation such as UGCG and UGT8, are actively contributing to many aspects of cancer signaling, proliferation, and resistance." (PMID 34637456, 2021). "Since glucose is an important energy source for cells and cancer cells are known for upregulating their glucose uptake, we measured the intracellular glucose concentration of MCF-7/UGCG OE and control cells." (PMID 31666638, 2019). "The central gene is PIK3R1 in Module 0, which module contains eight DEGs related to classical cancer pathways (FCER1A, GNG11, IGF1, LIFR, PDK4, PIK3R1, RCAN2, and UGCG)." (PMID 31119098, 2019). "Using elegant precedence of ganglioside-mediated activation of growth factor receptor signaling, our work reveals that increased GD3 gangliosides in response to altered expression of UGCG boost the EGFR phosphorylation status and subsequent downstream growth signaling in luminal cancers." (PMID 40934285, 2025). "Expression analysis revealed that RICTOR, UGCG, and ZFX were highly expressed in cancer cells." (PMID 40934285, 2025). "Increased expression of glucosylceramide synthase (GCS) contributes to drug resistance and the progression of various cancers; the expression profiles of GCS (UGCG) and the genes for glucocerebrosidases 1, 2, and 3 (GBA1, GBA2, and GBA3) were therefore studied in CCA." (PMID 35330102, 2022). "Our data show that increased UGCG expression itself does not induce pro-cancerous processes in normal liver cells, which indicates that increased GlcCer expression leads to different outcomes in different cancer types." (PMID 34626204, 2021). "Knockout of these genes, such as SLC35D1 and UGCG, would not directly affect the cancer cell growth, but could alter the micro-environment of cancer cells." (PMID 32085724, 2020).
tumor (27 papers, 2008 to 2025). "Preclinical studies consistently demonstrate that inhibition of UGCG attenuates key malignant phenotypes, including suppression of tumor cell proliferation, inhibition of metastatic spread, reduction in immune cell infiltration, and impairment of tumor-associated angiogenesis." (PMID 41155172, 2025). "Elevated UGCG expression has been associated with enhanced activity of downstream effectors, including nuclear factor kappa-light-chain-enhancer of activated B cells (NF-κB) and the canonical Wnt pathway (Wnt/β-catenin), which are known to promote tumor progression." (PMID 41155172, 2025). "Upregulation of UGCG is frequently observed in tumor cells, where it contributes to drug resistance, survival signaling, and malignant transformation." (PMID 41155172, 2025). "Beyond lysosomal disorders, dysregulation of UGCG, the rate-limiting enzyme for GlcCer biosynthesis, is frequently observed across multiple malignancies and strongly correlates with tumor progression, metastatic potential, and multidrug resistance." (PMID 41155172, 2025). "This effectively suggests that systematic effort in manipulating gangliosides via UGCG or GD3 synthesizing enzymes can serve as a strategy to prevent the activation of multiple RTKs that network for accelerated tumor growth in the luminal subtype." (PMID 40934285, 2025). "Differential gene expression data analysis showed that luminal A and B tumor tissues have significantly higher expression of UGCG and ZFX than basal and HER2+ groups." (PMID 40934285, 2025). "We now asked how RICTOR regulates the UGCG expression and how UGCG-mediated glucosylceramide synthesis enhances tumor progression." (PMID 40934285, 2025). "Tumor cells exploit UGCG and downstream GSL enzymes to produce immunosuppressive gangliosides like GM3 and GD3." (PMID 40903462, 2025). "Animal studies further validated that silencing of UGCG in MCF-7_ZFXOE tumors led to a decrease (1.5-fold) in the tumor growth of MCF-7_ZFXOE tumors." (PMID 40934285, 2025). "We observed an abundant increase in RICTOR expression and high expression of pAKT and UGCG in tumor tissues." (PMID 40934285, 2025). "Conversely, pharmacological inhibition of these signaling axes attenuates the tumor-promoting effects observed in UGCG-overexpressing models, indicating that altered glycosphingolipid metabolism can sustain oncogenic signaling in a feed-forward manner." (PMID 41155172, 2025). "To elucidate the effect of ZFX-mediated UGCG regulation on cell proliferation and tumor progression, we compared the cell proliferation rates of MCF-7_ZFXOE and MCF-7_ZFXSL cells." (PMID 40934285, 2025). "Our study, on the other hand, unraveled and validated that ZFX, a key C2H2-type, ZNF family transcription factor, mediates UGCG expression and thereby modulates sphingolipid and ganglioside metabolism and tumor progression." (PMID 40934285, 2025). "Deletion of UGCG almost completed blocked xenograft tumor growth, an effect that was much more robust than the effect on in vitro anchorage-independent growth." (PMID 36709325, 2023). "Concordant with the xenograft experiments, deletion of UGCG in KPC cells significantly reduced tumor growth compared to controls and prolonged survival of the orthotopically transplanted mice." (PMID 36709325, 2023). "UGCG silencing strongly also inhibited tumor spheroid growth in Lovo cells and moderately in HCT116 cells." (PMID 34638879, 2021). "Diethylnitrosamine (DEN)-induced liver tumors in mice, which exhibit a liver specific UGCG knockout (KO), show delayed tumor growth." (PMID 34626204, 2021). "In summary, these data reveal that UGCG OE reduces expression of tumor cell markers on normal liver cells." (PMID 34626204, 2021). "The expression of UGCG in tumorous tissue was in this data set again higher than in normal control liver tissue; healthy-donor, n=5; tumor, n=60; p<0.001." (PMID 29312601, 2017).
tumor (continued). "Importantly, pharmacological inhibition of these pathways has been shown to suppress UGCG-driven tumor growth in preclinical models." (PMID 41155172, 2025). "Therefore, UGCG and its branches emerges as a tunable metabolic checkpoint governing immune activation and tumor immune evasion." (PMID 40903462, 2025). "UGCG supports tumor survival through two distinct mechanisms." (PMID 40903462, 2025). "Finally, NF-κB activation sustains UGCG expression under inflammatory stress, integrating immune and stress signals with tumor-promoting lipid remodeling." (PMID 41155172, 2025). "Ceramide-glucosylceramide rheostat plays a crucial role in tumor progression, drug resistance, and chemotherapeutic response, where synthesis of glucosylceramides from ceramides is catalyzed by UGCG, and glucosylceramidase (GBA) hydrolyzes glucosylceramides to ceramides." (PMID 40934285, 2025). "Therefore, AKT/RICTOR-mediated phosphorylation of DNMT1 and/or KDM5A regulates gene expression, including that of UGCG, leading to an increase in glucosylceramides and enhanced tumor progression." (PMID 40934285, 2025). "Finally, Indian patient tumor tissues with high RICTOR expression also manifest high UGCG and ZFX expression, emphasizing the role of mTORC2-regulated ganglioside metabolism in tumor development." (PMID 40934285, 2025). "Histochemistry of tumor sections also showed that deletion of UGCG significantly reduced levels of phosphorylated MEK (p-MEK) and p-ERK but did not affect levels of ribosomal p-S6 and p-AKT, indicative of selective downregulation of RAF-MEK-ERK signaling cascades." (PMID 36709325, 2023). "Following UGCG overexpression (OE), NMuLi cells show decreased mitochondrial respiration and glycolysis accompanied by increased mitochondrial superoxide levels and decreased tumor marker expression (graphical abstract)." (PMID 34626204, 2021). "We further demonstrate that RICTOR regulates the synthesis of GD3 gangliosides through ZFX and UGCG, and triggers the activation of the EGFR signaling pathway, thereby promoting tumor growth." (PMID 40934285, 2025). "As UGCG has emerged as a key therapeutic target, we targeted the inhibition of UGCG using the FDA-approved UGCG inhibitor Eliglustat in MCF-7 and BT-474 tumor models upon intraperitoneal delivery." (PMID 40934285, 2025). "Metadata analysis further confirmed that luminal A and luminal B tumor tissues have higher UGCG and ZFX expression over other subtypes as observed in the TCGA data set, and expression of UGCG and ZFX is also high in ER+ and PR+ tumor tissues." (PMID 40934285, 2025). "UGCG, UDP-glucose ceramide glucosyltransferase, inhibition significantly enhances cell death in tumor cells." (PMID 40394027, 2025). "Instead, nude mice studies showed that silencing the UGCG gene in adriamycin-resistant MCF-7 cells, which overexpress the UGCG, inhibits tumor xenograft growth in vivo." (PMID 29409484, 2018). "Finally, we quantified the expression of UGCG and ZFX from luminal tumors by qRT-PCR, and observed ~2-fold increase in the expression of ZFX and UGCG in tumor tissues over adjacent matched normal control." (PMID 40934285, 2025). "Synthesis of glucosylceramides from ceramides is catalyzed by UDP-Glucose Ceramide Glucosyltransferase (UGCG), and ceramide-glucosylceramide rheostat connecting sphingolipid and ganglioside metabolism plays a crucial role in tumor progression, drug resistance, and chemotherapeutic response." (PMID 40934285, 2025). "To investigate early onset of UDP-glucose ceramide glucosyltransferase (UGCG)-mediated pro-cancerous changes in normal liver cells, we overexpressed UGCG in NMuLi cells, analyzed several key cellular processes and measured the expression of tumor markers." (PMID 34626204, 2021).
tumor (continued). "Furthermore, tumor markers such as FGF21 and EPCAM are lowered following UGCG OE, which could be related to glucosylceramide (GlcCer) and lactosylceramide (LacCer) accumulation in glycosphingolipid-enriched microdomains (GEMs) and subsequently altered signaling protein phosphorylation." (PMID 34626204, 2021).
infection (10 papers, 2011 to 2024). The state of being infected such as from the introduction of a foreign agent such as serum, vaccine, antigenic substance or organism. "By both pharmacological inhibition and genetic ablation, cells deficient in UGCG activity were found to display reduced entry and infection by influenza virus as well as entry mediated by the glycoproteins of other endosome-entering viruses including EBOV." (PMID 32032363, 2020). "When we treated target cells with PPMP, a broadly utilized inhibitor of UGCG, we observed a decrease in infection by PR8 influenza virus encoding NS1-GFP, as monitored by flow cytometry for GFP expression." (PMID 32032363, 2020). "The infection resulted in the overexpression of glucosylceramide (GlcCer) synthase (UGCG) and the specific accumulation of GlcCer and its subsequent incorporation into viral progeny." (PMID 38300320, 2024). "To further investigate the potential involvement of GlcCer in the spread of UUKV in tissue culture, we next assessed the ability of chemical inhibitors of UGCG to prevent UUKV infection." (PMID 38300320, 2024). "We then exposed cells with silenced UGCG to UUKV at a multiplicity of infection (MOI) of 0.1 for 24 h." (PMID 38300320, 2024). "A role for UGCG has also been proposed in infection by the unrelated influenza virus, Sindbis virus, and severe acute respiratory syndrome coronavirus 2, SARS-CoV-2." (PMID 38300320, 2024). "The reason is probably that UGCG was overexpressed upon infection compared with β4Galt5 and β4Galt6, the two LacCer synthases responsible for the conversion of GlcCer to LacCer." (PMID 38300320, 2024). "Our data imply that UGCG inhibitors inhibit the SVNI infection cycle after viral attachment and before translation of genome-encoded proteins." (PMID 37168733, 2023). "The most efficient inhibition was obtained when UGCG inhibitors were added before or at the time of infection." (PMID 37168733, 2023). "Here we used CRISPR/Cas9 to genetically knockout UGCG and thereby determine its role in influenza virus entry and infection." (PMID 32032363, 2020). "The weak effect of siUGCG #2 on UGCG protein expression correlates with the more modest decrease in infection with rVSV-SFTSV." (PMID 28388693, 2017). "As a positive control, siRNAs targeting UGCG were also included and infection of rVSV-SFTSV and SV40 decreased similar to previous experiments." (PMID 28388693, 2017). "To evaluate this possibility, we first monitored UGCG expression after infection." (PMID 38300320, 2024). "In addition to RNAi approaches, we also tested the effects of rVSV-SFTSV infection in HAP1 UGCG knockout cells (UGCG KO)." (PMID 28388693, 2017). "Certain tick cells lines, including those belonging to the Ixodidae family, are amenable to siRNA knockdown and future investigations will assess whether UGCG is important for infection with SFTSV within its arthropod vector." (PMID 28388693, 2017). "When UGCG was silenced, UUKV infection was reduced by 60–70% in cells carrying either UGCG siRNA compared with that in the control cells transfected with nontargeted control siRNA." (PMID 38300320, 2024). "We showed that UGCG expression and enzymatic activity are important for SFTSV entry, using both rVSV-SFTSV and wild-type SFTSV infection." (PMID 28388693, 2017). "Similar to previous results, rVSV-SFTSV exhibited a dose-dependent decrease in infection, and consistent with the siRNA experiment, VSV-HRTV infection was negatively impacted by UGCG inhibition with NB-DNJ." (PMID 28388693, 2017). "Collectively, these results show that UGCG and its product GlcCer are essential for HRTV infection." (PMID 36920967, 2023). "The present study shows that SVNI induce an alteration in the levels of SLs early after infection both in vitro and in vivo, and this alteration appears to play a role in SVNI replication, as indicated by the finding that UGCG inhibitors reduced viral replication in vitro." (PMID 37168733, 2023).